HDAC3 (histone deacetylase 3)
Diseases named in the same sentence as HDAC3 in open-access papers (continued):
Sharing a sentence is not in itself a finding about the gene and the disease.
COVID-19 (1 paper, 2023). A disease caused by infection with severe acute respiratory syndrome coronavirus 2. "In this study, we analyzed the expression profile of DNMTs (DNMT1, DNMT3A, DNMT3B) and HDACs (HDAC2 and HDAC3) in COVID-19 patients." (PMID 36840831, 2023). "We conducted a case-control study to investigate the differential expression of DNMT1, DNMT3A, DNMT3B, HDAC2, and HDAC3 in the blood of 120 patients (30 mild, 30 moderate, 30 severe, and 30 critical) and 30 healthy subjects without COVID-19." (PMID 36840831, 2023). "In contrast to previous reports, DNMT3A and DNMT3B expression was found to be significantly downregulated in COVID-19 cases, whereas DNMT1, HDAC2, and HDAC3 expression did not change." (PMID 36840831, 2023).
diabetic retinopathy (1 paper, 2020). "The correlation between HDAC3 and retinal ganglion cells in diabetic retinopathy is still unclear yet." (PMID 32190700, 2020). "The results indicated that HDAC3 could be related to the apoptosis and autophagy of retinal ganglion cells in diabetic retinopathy." (PMID 32190700, 2020). "However, the correlation between HDAC3 and retinal ganglion cells in diabetic retinopathy is still unclear yet." (PMID 32190700, 2020).
ductal carcinoma in situ (1 paper, 2025). "The results showed that BroccoMax supplementation significantly reduced tissue biomarkers, such as Ki-67 and HDAC3, in benign tissue, but not in ductal carcinoma in situ (DCIS) or invasive ductal carcinoma tissue." (PMID 40231924, 2025).
Emphysema (1 paper, 2023). "Our results were different from those studies, as there was a decrease in HDAC3 expression only in patients with the emphysema phenotype and with moderate and severe severity." (PMID 37373058, 2023). "Furthermore, only emphysema patients showed a significant reduction in HDAC3 expression, and only COPD unclassified have a significantly increased expression in the HDAC4 gene." (PMID 37373058, 2023). "Additionally, HDAC2 expression was reduced in patients with emphysema and exacerbator, along with a reduced HDAC3 expression in patients with emphysema." (PMID 37373058, 2023). "Emphysema and exacerbator present significant reduction in HDAC2 expression, and only emphysema showed HDAC3 reduction." (PMID 37373058, 2023).
endotoxemia (1 paper, 2024). "The HDAC3 inhibitors protected wild-type or Hipk2 BMs-reconstituted mice from LPS-induced endotoxemia." (PMID 39040100, 2024).
epilepsy (1 paper, 2024). A brain disorder characterized by episodes of abnormally increased neuronal discharge resulting in transient episodes of sensory or motor neurological dysfunction, or psychic dysfunction. "The impressive data supporting the role of deacetylation by HDACs in epilepsy arises from the study that the interaction of HDAC3 with MADS-box domain of MEF2 results in MEF2 deacetylation in nucleus and the decrease of MEF2 transcription." (PMID 39563472, 2024). "In the WAG/Rij epilepsy rat model, a genetic model of absence epilepsy, epileptogenesis, and mild-depression comorbidity, the acetylated levels of H3 and H4 histones were increased significantly and the decreased expressions of HDAC1 and HDAC3 were observed following NaB treatment." (PMID 39563472, 2024).
gastric tumor (1 paper, 2023). "Quantification of parietal peritoneum metastasis of gastric tumor cells by Honokiol and gene silencing HDAC3 revealed that Honokiol had no toxic effects and had modest gains in body weight." (PMID 34973135, 2023).
head and neck squamous cell carcinoma (1 paper, 2020). A squamous cell carcinoma that arises from any of the following anatomic sites: lip and oral cavity, nasal cavity, paranasal sinuses, pharynx, larynx, and salivary glands. "In head and neck squamous cell carcinoma (HNSCC) cells, H3K4ac modulated by HDAC3 is enriched around the transcription start site of EMT related genes such like GLI1 and SMO, co-overexpression of which promotes HNSCC cell invasion and migration ability." (PMID 33262941, 2020).
hematoma (1 paper, 2026). A hematoma is a collection of blood from a vascular structure into an extravascular space. "Moreover, conditional deletion of HDAC3 in microglia did not alter hematoma volume after ICH, suggesting that the observed effects are independent of hematoma size." (PMID 41815335, 2026).
HIV-1 infection (1 paper, 2014). The type species of lentivirus and the etiologic agent of acquired immunodeficiency syndrome (AIDS). "Taken together these findings suggest that HDAC3 is an essential target to disrupt HIV-1 latency, and inhibition of HDAC2 may also contribute to the effort to purge and eradicate latent HIV-1 infection." (PMID 25136952, 2014).
insulinoma (1 paper, 2021). "This is in line with studies showing that butyrate has anti-cancer activity and a study in the rat insulinoma (RIN) cell line, but in contrast to studies in diabetic rodents where butyrate or a HDAC3 inhibitor increased beta cell proliferation." (PMID 34638768, 2021).
intestinal inflammation (1 paper, 2023). "Loss of HDAC3-dependent epithelial MHCII led to elevated commensal-specific Th17 activity and increased susceptibility to microbiota-driven intestinal inflammation." (PMID 36602872, 2023).
Intraventricular hemorrhage (1 paper, 2024). Bleeding into the ventricles of the brain. "Though RGFP966 is being widely used for selectively targeting HDAC3, a study used BRD3308 to selectively inhibit HDAC3 in a mouse model after intraventricular hemorrhage." (PMID 39050859, 2024).
invasive carcinoma (1 paper, 2008). A carcinoma that is not confined to the epithelium, and has spread to the surrounding stroma. "Lesions of high-grade PIN in the vicinity of invasive carcinomas were identified in 56 (HDAC1), 57 (HDAC2) and 67 (HDAC3) cases, respectively." (PMID 18212746, 2008). "Expression of HDACs in high-grade PIN was almost identical with the strength of expression in the corresponding invasive carcinomas (HDAC1: r=0.961, P<0.001, HDAC2: r=0.756, P<0.001, HDAC3: r=0.694, P<0.001), indicating that HDAC overexpression is an early event in prostate carcinogenesis." (PMID 18212746, 2008).
iron deficiency (1 paper, 2021). "Hepcidin could promote M1-like macrophage polarization; thus, it is possible that iron deficiency inhibits M1-like phenotype by lowering hepcidin expression via enhancing HDAC3 binds chromatin at the hepcidin locus." (PMID 34054839, 2021). "Intriguingly, during iron deficiency, RGFP966 (the HDAC3 inhibitor) counteracts hepcidin suppression." (PMID 34054839, 2021).
lipodystrophy (1 paper, 2021). A congenital or acquired disorder characterized by abnormal loss or redistribution of the adipose tissue in the body. "Three lipodystrophy-associated genes, Histone deacetylase 3 (HDAC3), Nuclear receptor subfamily 0 group B member 2 (NR0B2), and small ubiquitin-like modifier 1 (SUMO1) were also present in this network." (PMID 34017037, 2021).
liver disease (1 paper, 2023). "Especially it would be interesting to verify the link between hepatic expression of co-inhibitory receptors, genetic variation in HDAC3 and CYBRD1, and liver disease progression to HCC." (PMID 37632052, 2023). "Further studies are needed to determine the significance of HDAC3 and CYBRD1 in liver disease progression to HCC in CHC patients." (PMID 37632052, 2023).
Lymphatic Metastasis (1 paper, 2022). Transfer of a neoplasm from its primary site to lymph nodes or to distant parts of the body by way of the lymphatic system. "In Kaplan–Meier method, FIGO III-IV disease, lymphatic metastasis, HDAC3 high expression and FOXA1 high expression sighificantly decreased patients’ DFS in the univariate analysis (p < 0.001, = 0.001, < 0.001 and = 0.001, respectively)." (PMID 34991620, 2022).
lymphedema (1 paper, 2017). Excess fluid collection in tissues, causing swelling. "Our results demonstrate that endothelial inactivation of ubiquitously expressed Hdac3, but not Hdac1 or Hdac2, in mice causes embryonic lethality, failure of blood-lymph separation, lymphedema, and defects in both lymphatic and lymphovenous valves." (PMID 29035278, 2017). "Mice lacking endothelial Hdac3 demonstrate congenital lymphedema due to defective lymphovenous and intraluminal lymphatic valve development." (PMID 29035278, 2017).
lymphoid leukemia (1 paper, 2023). A malignant lymphocytic neoplasm of B-cell or T-cell lineage involving primarily the bone marrow and the peripheral blood. "As such, the mechanism proposed here identifies HDAC3 inhibition as a potential therapeutic route for the treatment of ERG-driven and ERG-dependent myeloid and lymphoid leukemias." (PMID 37735473, 2023).
mammary adenocarcinomas (1 paper, 2023). "Such an association of HDAC3 levels with higher tumor grade has also been observed in colorectal and mammary adenocarcinomas." (PMID 36901692, 2023).
maxillary cancer (1 paper, 2020). "Suppression of HDAC3 enhances apoptosis induced by paclitaxel in human maxillary cancer cells." (PMID 32571203, 2020).
metastasis (1 paper, 2020). The spread or migration of cancer cells from one part of the body (where they first appeared) to another. "The univariate results of Cox regression analysis showed that increased tumor size/nuclear HDAC3/cytoplasmic HDAC3 were significantly associated with earlier occurrence of brain metastasis, while positive ER or PR was associated with delayed brain metastasis." (PMID 32686908, 2020).
migraine (1 paper, 2023). "Differentially methylated CpGs were also detected in the genes HDAC1 and HDAC3 among sites with nominal association (p < 0.05) with reduced headache and migraine days in our study." (PMID 38087366, 2023).
myeloid leukemia (1 paper, 2019). A clonal proliferation of myeloid cells and their precursors in the bone marrow, peripheral blood, and spleen. "Others also report that a pharmacological interference with HDAC3 triggers replication stress, DNA damage, cell death, and enhanced chemosensitivity of lymphocytic and myeloid leukemia cells." (PMID 31561534, 2019).
Myocardial fibrosis (1 paper, 2023). "Interestingly, although most of the current studies show that HDAC3 seems to play an evil role in many cardiovascular diseases, and pharmacological or genetic inhibition of HDAC3 can improve MI, myocardial fibrosis, and myocardial remodeling, HDAC3 also is essential for heart development." (PMID 37072432, 2023).
nephrolithiasis (1 paper, 2025). The presence of a calculus in the pelvis of the kidney; this is most often composed of mineral salts and proteins. "CaOx treatment reduced RXRα expression and derepressed SMART/HDAC3 suppressors, leading to enhancer activation and increased expression of those genes that promote nephrolithiasis." (PMID 40091688, 2025). "Mechanistically, under normal circumstances, RXRα inhibited nephrolithiasis‐promoting genes by recruiting the HDAC3/SMART complex to repress enhancer activity." (PMID 40091688, 2025). "Additionally, we found that RXRα recruited the SMART/HDAC3 co‐repressor complex to inhibit the transcription of these nephrolithiasis‐promoting genes." (PMID 40091688, 2025). "To investigate whether RXRα recruits SMRT and HDAC3, we conducted ChIP‐qPCR experiments to assess the binding of SMRT, and HDAC3 on the representative Bex‐inhibited/RXRα‐bound nephrolithiasis‐promoting genes in TECs." (PMID 40091688, 2025).
non-alcoholic steatohepatitis (1 paper, 2019). "Here we demonstrate that G protein pathway suppressor 2 (GPS2), a subunit of the nuclear receptor corepressor (NCOR) and histone deacetylase 3 (HDAC3) complex, has a central role in these alterations and accelerates the progression of NAFLD towards non-alcoholic steatohepatitis (NASH)." (PMID 30975991, 2019).
pancreatic adenocarcinoma (1 paper, 2009). "Pancreatic adenocarcinoma displayed strong nuclear immunoreactivity for HDAC1 (32%), HDAC2 (63%), HDAC3 (79%) and RelA/p65 (45%) in a considerable number of cases." (PMID 19912635, 2009).
pemphigus (1 paper, 2024). Pemphigus is a group of rare autoimmune diseases that cause blistering of the skin and mucous membranes (mouth, nose, throat, eyes, and genitals).This conditioncan occur at any age, but often strikes people in middle or older age. "Together, by addressing HDAC3 and KLF5, we present an option to modulate intercellular adhesion both under homeostatic conditions as well as in the pemphigus disease setting." (PMID 39271654, 2024). "Here we exploited HDAC3- and KLF5-dependent regulation of DSG3 transcription, which was identified by our screens, to rescue DSG3 protein levels and membrane localization in pemphigus models." (PMID 39271654, 2024).
pemphigus vulgaris (1 paper, 2024). Pemphigus is a group of chronic autoimmune skin diseases characterized by blister formations on the outer layer of the skin and the mucous membranes. "Together, KLF5 and histone deacetylase 3 are regulators of desmoglein 3 gene expression and intercellular adhesion and represent potential therapeutic targets in pemphigus vulgaris." (PMID 39271654, 2024). "Inhibiting histone deacetylase 3 increases KLF5 levels and protects against the deleterious effects of autoantibodies in murine and human pemphigus vulgaris models." (PMID 39271654, 2024).
peritonitis (1 paper, 2025). Inflammation of the peritoneum (tissue that lines the abdominal wall and covers most of the organs in the abdomen). "IKZF1 exacerbates macrophage inflammation in CLP-induced peritonitis by epigenetically silencing SDHB via HDAC3-mediated deacetylation, thereby disrupting mitochondrial metabolism and amplifying pro-inflammatory signals." (PMID 41019036, 2025). "Overall, IKZF1 collaborates with HDAC3 to inhibit Sdhb expression, which in turn exacerbates macrophage inflammatory responses triggered by peritonitis." (PMID 41019036, 2025). "In this study, we discovered that IKZF1 collaborates with HDAC3 to regulate the H3K9ac modification, thereby affecting the functional transition of macrophages and participating in the pathological process of acute peritonitis." (PMID 41019036, 2025).
pheochromocytoma (1 paper, 2021). "Here we report that exposure of rat pheochromocytoma (PC)-12 cells to IH in vitro exhibited reduced HDAC enzyme activity due to proteasomal degradation of HDAC3 and HDAC5 proteins." (PMID 34079475, 2021).
pilocytic astrocytoma (1 paper, 2022). Pilocytic astrocytoma is a rare subtype of low-grade glioma of the central nervous system characterized by a well circumscribed, often cystic, brain tumor with a discrete mural nodule and long, hair-like projections that extend from the neoplastic astrocytes. "Gutmann has observed a 2.483-fold increase in HDAC3 in pilocytic astrocytoma than in normal samples (p = 0.021)." (PMID 35359455, 2022).
Pituitary Adenomas (1 paper, 2022). "We also examined HDAC1, HDAC2, and HDAC3 expression by qRT-PCR in six GH-secreting, six ACTH-secreting, and six PRL-secreting human pituitary adenomas." (PMID 35646715, 2022).
pituitary tumor (1 paper, 2022). A benign or malignant neoplasm affecting the pituitary gland. "Because the increase of HDAC2 and HDAC3 levels in pituitary tumors were similar, and there is no HDAC2-specific inhibitor available, we decided to focus our subsequent studies on HDAC3." (PMID 35646715, 2022).
polycystic ovary syndrome (1 paper, 2019). A disorder that manifests as multiple cysts on the ovaries. "One exception is a study showing that the level of histone deacetylase 3 (HDAC3) was increased in GCs retrieved from polycystic ovary syndrome patients who experienced in vitro fertilization (IVF) failure compared with those from patients who experienced successful IVF14." (PMID 31844300, 2019).
Premature ovarian insufficiency (1 paper, 2026). Amenorrhea due to loss of ovarian function before the age of 40. "Constitutively low HDAC3 expression in pGCs is essential for PF survival: conditional deletion of Hdac3 caused profound PF depletion and ultimately premature ovarian insufficiency." (PMID 41803516, 2026).
pulmonary arterial hypertension (1 paper, 2019). Pulmonary arterial hypertension (PAH) is a group of diseases characterized by mean pulmonary artery pressure >20 mmHg and elevated pulmonary arterial resistance leading to right heart failure. "In contrast, increased expression of HDAC3, HDAC4, and HDAC5 is associated with induction of Nox2 and Nox4 in pulmonary arterial hypertension, which was decreased by the HDAC inhibitor, valproic acid." (PMID 31223486, 2019).
retinal (1 paper, 2023). "One study showed that HDAC3 accounts for 42% of the rat retina total HDAC activity, yet, the study did not detect a change in HDAC3 activity at 24 h after retinal IR injury." (PMID 37735154, 2023).
skin aging (1 paper, 2025). The gradual irreversible changes in structure of skin that occur as a result of the passage of time.. "In conclusion, this study illustrates that macrophages play a critical role in lactate‐induced collagen synthesis in the skin, and targeting the lactate‐H4K12la‐HDAC3‐TGF‐β axis may represent a novel approach for enhancing collagen production to combat skin aging." (PMID 39945346, 2025).
skin inflammation (1 paper, 2025). "Additionally, blocking HDAC3 has been associated with reduced IL-33 expression and improved AD-like skin inflammation." (PMID 40612737, 2025).
synovial sarcoma (1 paper, 2009). "All HDAC inhibitors previously shown tokill synovial sarcoma cells include HDAC3 among their specifictargets." (PMID 19325926, 2009).
tauopathy (1 paper, 2021). Neurodegenerative disorders involving deposition of abnormal tau protein isoforms (tau proteins) in neurons and glial cells in the brain. "Moreover, HDAC3 promotes tauopathy, whereas suppression of HDAC3 may affect not only nonamyloidogenic APP processing but also neuroprotective gene expression in vitro and in an AD mouse model." (PMID 33483607, 2021).
Thrombocytopenia (1 paper, 2023). A reduction in the number of circulating thrombocytes. "In addition, the histone deacetylase 3 gene SNP (rs2530223 C>T) was found to be associated with increased susceptibility to ITP in all genetic models, with TC/TT genotypes associated with severe thrombocytopenia in the Han population." (PMID 36902438, 2023).
thymic carcinoma (1 paper, 2023). Thymic carcinoma (TC) is a type of thymic epithelial neoplasm characterized by a high malignant potential. "Variations were also observed in HDAC3 staining among different WHO subtypes, as nuclear immunoreactivity was less frequent in the more aggressive thymic carcinomas, compared to the rest of the TETs categories (Fisher exact test, p = 0.044)." (PMID 36901692, 2023).
thyroid (1 paper, 2013).
urothelial carcinoma (1 paper, 2014). A malignant neoplasm derived from the transitional epithelium of the urinary tract (urinary bladder, ureter, urethra, or renal pelvis). "High HDAC expression levels were found in 40 to 60% of all investigated urothelial carcinomas (HDAC-1: 40%, HDAC-2: 42%, HDAC-3: 59%)." (PMID 24624923, 2014).
uterine cancer (1 paper, 2024). Primary or metastatic malignant neoplasm involving the uterine corpus and/or the cervix. "Taken together, the increased expression levels of HDAC3 in colorectal, breast, and uterine cancers and the GO analysis results of the genes with expression levels positively correlated with those of HDAC3 suggested that HDAC3 may play a crucial role in cancer development and malignancy." (PMID 38805168, 2024).